IL6R (interleukin 6 receptor)
Diseases named in the same sentence as IL6R in open-access papers (continued):
Sharing a sentence is not in itself a finding about the gene and the disease.
crescentic glomerulonephritis (1 paper, 2020). A histopathologic term for a pattern of diseases characterized by extensive crescent formation in the glomeruli; patients present clinically with rapid deterioration of renal function, and possible progression to end-stage renal failure within weeks or months. "Our study has revealed a new remission mechanism whereby effector Tregs migrate into the crescentic glomerulonephritis via the CCL22/17–CCR4 axis that is facilitated by M2‐like type macrophages that are induced by IL‐6R blockade." (PMID 33163184, 2020).
cyst (1 paper, 2023). A sac-like closed membranous structure that may be empty or contain fluid or amorphous material. "Identification of high levels of IL-6R and IL-6 in both tumor tissue and cyst fluid has provided the impetus for trialing treatment of ACP with tocilizumab, a humanized monoclonal antibody against IL-6R." (PMID 37886179, 2023).
demyelinating disease (1 paper, 2014). A broad group of disorders that affect the myelin sheaths that cover the neurons. "Because anti-tumour necrosis factor therapy can exacerbate demyelinating disease, the anti-interleukin-6 receptor antibody tocilizumab was started at 8 mg/kg every 4 weeks." (PMID 25216562, 2014).
dengue (1 paper, 2023). "Polymorphisms in the IL4R and IL6R cytokine receptors were also pinpointed as risk factors for clinical dengue in Colombian children, as these may introduce changes in the T cells signal transduction, and thus alter the activation of Th subtypes in dengue." (PMID 38076464, 2023).
dilated cardiomyopathies (1 paper, 2021). "Although ADAM17's expression is downregulated in physiological states, several studies have demonstrated its upregulation along with its substrates [tumor necrosis factor-alpha (TNFα) and soluble interleukin-6 receptor (sIL-6R)] in dilated cardiomyopathies." (PMID 34150874, 2021).
Disseminated intravascular coagulation (1 paper, 2022). Disseminated intravascular coagulation is characterized by the widespread activation of coagulation, which results in the intravascular formation of fibrin and ultimately thrombotic occlusion of small and midsize vessels. "The mechanism of action of TCZ depends on its inhibitory effect of IL-6R, therefore decreasing IL-6 mediated increased vascular permeability, immune cells activation, histamine release from mast cells, activation of coagulation, and development of disseminated intravascular coagulation (DIC)." (PMID 35203844, 2022).
Ebola (1 paper, 2020). "Overall our data suggest that human clinical trials evaluating the benefits of α-IL-6 mAbs versus α-IL-6R mAbs titversus combined early α-IL-6 mAb and later α-IL-6R mAb is warranted to evaluate the potential of IL-6 pathway blockade in the during Ebola or SARS-CoV-2 infection." (PMID 33071786, 2020).
empyema (1 paper, 2025). An accumulation of pus in a body cavity, usually the pleural space. "Steiger testing was supportive of the conclusion that SNPs included in the IV were affecting IL-6R signalling and this exposure was responsible for the affect on the risk of empyema development." (PMID 40819633, 2025).
endometritis (1 paper, 2016). An acute or chronic, usually bacterial infectious process affecting the endometrium. "Furthermore, these findings could be translated to use of inhibitors of STAT3/IL6R signaling in the uterus to limit the severity of endometritis." (PMID 26813342, 2016). "However, during uterine infection, TLR4 cross-talk with the IL6R pathway may perturb this balance and these concepts need to be explored further." (PMID 26813342, 2016).
enteritis (1 paper, 2025). Inflammation of the small intestine. "After treatment with IL-6R Ab to block the function of IL-6, the symptoms of enteritis obviously reduced base on the H&E staining of intestine tissue." (PMID 40005679, 2025).
epilepsy (1 paper, 2018). A brain disorder characterized by episodes of abnormally increased neuronal discharge resulting in transient episodes of sensory or motor neurological dysfunction, or psychic dysfunction. "Specifically, IL-6 and IL6R are closely associated with neurological excitability; thus, it has been proposed that this pathway may be involved in epilepsy." (PMID 29958461, 2018). "Another gene overexpressed in children with epilepsy was IL6R, whose promoter region contains a CRE sequence." (PMID 29958461, 2018).
experimental autoimmune encephalomyelitis (1 paper, 2022). An autoimmune demyelinating disease of the central nervous system that is produced experimentally in animals by the injection of homogenized brain or spinal cord in Freund's adjuvant. "A deleterious role of IL-6 signaling in MS has been further demonstrated in studies in experimental autoimmune encephalomyelitis (EAE) mice where IL-6R blockade prevents the development of EAE in IL-6 sufficient mice and IL-6 -/- mice are resistant to EAE." (PMID 35386698, 2022).
female infertility (1 paper, 2024). Diminished or absent ability of a female to achieve conception. "It would be interesting for us to further illuminate the deeper mechanism underlying the function of IL6R, CD274 and CASR, and also HA/NA PCOS classification markers on the formation of PCOS and female infertility." (PMID 38347589, 2024). "Also from the knowledge graph, we noticed the important role for our newly discovered HA and NA PCOS functional markers IL6R, CD274 and CASR on female infertility." (PMID 38347589, 2024).
gastric disease (1 paper, 2021). "Helicobacter pylori (H. pylori) induces an intense inflammatory response, mediated by proinflammatory cytokines, including interleukin (IL)-6 and its membrane receptor (IL-6R), which activates important signaling pathways in the development of gastric disease and cancer." (PMID 34008757, 2021).
geographic atrophy (1 paper, 2025). "Interventional human evidence supports immunity as a therapeutic target: complement inhibition slows geographic atrophy; anti-VEGF reduces leak; intravitreal corticosteroids suppress inflammatory edema; and anti-TNF/IL-6R improve refractory NIU." (PMID 41394857, 2025).
Gilbert syndrome (1 paper, 2022). An autosomal recessive inherited disorder characterized by unconjugated hyperbilirubinemia, resulting in harmless intermittent jaundice. "Our findings are consistent with previous observations in patients treated with tocilizumab, another IL-6Rα inhibitor, and suggest that IL-6 pathway inhibition leads to decreased UDP-glucuronosyltransferase 1-1 activity in Gilbert’s syndrome patients." (PMID 35149777, 2022).
graft versus host disease (1 paper, 2014). An immune system disorder that occurs after allogeneic hematopoietic stem cell transplant and is a reaction of donor immune cells against host tissues. "In graft-versus-host disease, the blockade of IL-6R-mediated signaling increases Treg-cell numbers at the expense of Th1/17, dampening immune reactivity." (PMID 24185641, 2014).
granulomatosis with polyangiitis (1 paper, 2023). A small-vessel necrotizing vasculitis characterized by the association of inflammation of the vessel wall and peri- and extravascular granulomatosis. "We investigated the IL-6 receptor (IL-6R) expression on the surface of T cells isolated from peripheral blood mononuclear cells (PBMCs) of microscopic polyangiitis (MPA) and granulomatosis with polyangiitis (GPA) patients and measured the serum soluble IL-6R (sIL-6R) levels in these patients." (PMID 38002672, 2023).
hematoma (1 paper, 2025). A hematoma is a collection of blood from a vascular structure into an extravascular space. "Microglia-specific IL-6Rα deletion mirrored the anti-inflammatory and neuroprotective effects observed with TCC, reducing hematoma volume and improving sensory and behavioral outcomes." (PMID 40934970, 2025).
ileus (1 paper, 2022). Decrease in peristalsis in the absence of a mechanical bowel obstruction. "In a murine (C3H/HeOuJ) endotoxin-induced ileus model, IL-6 inhibition (IL-6R antibody) prevented late ileus development." (PMID 35805922, 2022).
invasive ductal carcinoma (1 paper, 2018). "High grade invasive ductal carcinoma (IDC) clinical specimen displayed elevated level of IL-6R and depleted MAO-A expression." (PMID 29695771, 2018).
iron overload (1 paper, 2024). "Taken together, the potential links of the key genes HIF-1α and DMT1 for iron overload, as well as the IL-6R/JAK/STAT pathway that affects aortic iron content and metabolism, are the focus of this research." (PMID 39247821, 2024). "Abnormal IL-6R first activates this noncanonical regulatory axis, resulting in iron overload and AD." (PMID 39247821, 2024).
liver cirrhosis (1 paper, 2017). "In conclusion, IL-6R was increased whereas miR-30b was decreased in patients with liver cirrhosis." (PMID 28953986, 2017). "In conclusion, IL-6R was upregulated while miR-30b was decreased in patients with liver cirrhosis." (PMID 28953986, 2017).
lower respiratory tract infections (1 paper, 2017). "One of the most common side effects of targeting either the IL-6R (via Tocilizumab) or IL-6 (via Siltuximab) is increased risk of both upper and lower respiratory tract infections." (PMID 28953978, 2017).
lymphopenia (1 paper, 2017). Reduction in the number of lymphocytes. "Thus, it is possible that the beneficial impact of anti–IL-6R treatment on the control of viral replication in our experiments may extend beyond the restriction of lymphopenia and NK cell death." (PMID 28240600, 2017).
meningioma (1 paper, 2026). A generally slow growing tumor attached to the dura mater. "Hsa-miR-21-5p enhanced proliferation and viability of KT21-MG1 meningioma cells and showed a regulatory effect on IL6R, IL6ST and other predicted target genes TIMP3, PIK3R, RHOB, and SASH1 by interacting with 3'UTRs." (PMID 42196381, 2026). "DNA hypomethylation-related overexpression of hsa-miR-21-5p contributes to aggressive meningioma growth by interaction with multiple target genes, and probably affects microenvironment communication between meningioma cells and BAMs by lowering the IL6R level in tumor tissue." (PMID 42196381, 2026). "IL6R and IL6ST are predicted targets of hsa-miR-21-5p downregulated in atypical/anaplastic meningiomas." (PMID 42196381, 2026).
mental disorder (1 paper, 2023). A disease that has its basis in the disruption of mental process. "Interestingly, the IL6R gene polymorphism (rs2228145) was associated with all three mental disorders." (PMID 37510364, 2023).
mesothelioma (1 paper, 2019). A usually malignant and aggressive neoplasm of the mesothelium which is often associated with exposure to asbestos. "The combination of IL-6 and IL-6Rα has been shown to drive VEGF production in mesothelioma cells; in the present study VEGF was significantly elevated in malignant PE as compared to benign PE, suggesting a contribution by tumor cells." (PMID 31741710, 2019). "The present study confirms earlier reports of high IL-6 in mesothelioma PE and of IL-6 plus IL-6Rα in NSCLC PE." (PMID 31741710, 2019).
microcephaly (1 paper, 2015). A congenital or acquired developmental disorder in which the circumference of the head is smaller than normal for the person's age and sex. "In three models, newborns with hyperEPO alone (IL-6R, VCAM-1, VEGF-R1, yellow) were at significantly greater risk of microcephaly than referent children." (PMID 25793991, 2015).
muscle tumors (1 paper, 2023). "In addition, 25 DPs are related to muscle tumors; 8 DPs (APOE, FCER1A, FCER2, GSK3B, HSPD1, IL6R, MMP7, and RARRES2) are linked to proliferation of muscle cells." (PMID 36918772, 2023).
muscular dystrophy (1 paper, 2017). Muscular dystrophy (MD) refers to a group of more than 30 genetic diseases characterized by progressive weakness and degeneration of the skeletal muscles that control movement. "As no adverse effects of treatment with the MR16-1 antibody were observed, our results indicate that the anti-IL-6R antibody is a potential therapy for muscular dystrophy particularly for promoting skeletal muscle regeneration." (PMID 29078808, 2017).
myelitis (1 paper, 2025). An inflammatory process affecting the spinal cord. "Similarly, high-dose IVMP combined with Interleukin-6-receptor blockade has shown improvements in disability in NMOSD patients with myelitis." (PMID 40292288, 2025).
myocarditis (1 paper, 2021). Myocarditis is a condition that is characterized by inflammation of the heart muscle (myocardium). "It is important to note that CS-refractory, infliximab-refractory, or MMF-refractory myocarditis responded very well to anti-IL6R therapy, which could further support the role of this therapy in the treatment of refractory myocarditis." (PMID 34686542, 2021). "Interestingly, our longitudinal profiling of the immune cells by global immune cell CyTOF panel with 40 markers reported for the first time a possible role of Th17 in ICI-related myocarditis, especially in patients 8 and 9, who had refractory myocarditis but responded to IL6R blockade therapy." (PMID 34686542, 2021).
myositis (1 paper, 2012). "In another model of PM, known as C-protein-induced myositis, intraperitoneal administration of anti-IL-6R Ab suppressed the severity of myositis preventatively as well as therapeutically." (PMID 22315615, 2012).
myxoma (1 paper, 2024). A benign soft tissue neoplasm characterized by the presence of spindle and stellate cells, lobulated growth pattern, and myxoid stroma formation. "Real-time PCR revealed that stimulation with IL-6 + soluble IL-6R (sIL6R) significantly increased IL-6 mRNA in the myxoma cells." (PMID 38396907, 2024). "Immunohistochemical staining and reverse transcription-polymerase chain reaction (RT-PCR) revealed that IL-6 and its receptors, IL-6 receptor (IL-6R) and gp130, co-existed in the myxoma cells." (PMID 38396907, 2024). "The addition of antibody against IL-6R or gp130 reduced the secretion of IL-6 from the myxoma cells." (PMID 38396907, 2024). "Immunocytochemical staining showed positive immunoreactivities for IL-6, IL-6R, and gp130 in the cultured myxoma cells." (PMID 38396907, 2024). "RT-PCR with specific primers demonstrated that both myxoma cells and HUVECs yielded positive products for IL-6, and its receptor complexes, IL-6R and gp130." (PMID 38396907, 2024). "In addition, the RT-PCR study showed the expressions of IL-6 mRNA, IL-6R mRNA, and gp130 mRNA in the myxoma cells, together with calretinin mRNA." (PMID 38396907, 2024).
nasal polyp (1 paper, 2023). "We confirmed the mRNA expression of the IL-6 receptor (comprising IL-6R and gp130 chains) and the type II OSM receptor (comprising OSMR and gp130 chains) but not the type I OSM receptor (comprising LIFR and gp130 chains) in nasal polyp-derived HNECs." (PMID 37047067, 2023).
Nephropathy (1 paper, 2018). A nonspecific term referring to disease or damage of the kidneys. "Increased signaling via TNFRs and IL6R is also involved in the pathophysiology of kidneys including nephropathy via production of MMPs in renal tissues." (PMID 29445381, 2018).
nephrotic syndrome (1 paper, 2023). A collection of symptoms that include severe edema, proteinuria, and hypoalbuminemia; it is indicative of renal dysfunction. "We report a series of three cases of nephrotic syndrome due to iMCD that helps to delineate the importance of early and continuous therapy with the anti-interleukin-6 receptor antibody tocilizumab." (PMID 36698794, 2023).
new-onset refractory status epilepticus (1 paper, 2020). "Novel tailored immunotherapies targeting specific cytokines (e.g., interleukin-1 receptor antagonist—anakinra, and interleukin-6 receptor inhibitor—tocilizumab) have been shown to be effective in new-onset refractory status epilepticus (NORSE) and febrile-infection related epilepsy syndrome (FIRES)." (PMID 32959201, 2020).
nonalcoholic steatohepatitis (1 paper, 2024). "The particular polymorphism in IL6R, rs2228145, contributes to the genetic predisposition of nonalcoholic steatohepatitis, and a variation of hematological levels." (PMID 38785970, 2024).
oedema (1 paper, 2024). "The effects of the IL‐1R and IL‐6R antagonists were evaluated by assessing the general and pulmonary condition of the mice, lung injury scores, pulmonary oedema formation, and inflammatory response on D7 after bleomycin challenge." (PMID 38594909, 2024).
osteomyelitis (1 paper, 2025). An acute or chronic inflammation of the bone and its structures due to infection with pyogenic bacteria. "We next investigated the clinical significance of PCD pathways by correlating their GSVA scores with representative inflammatory biomarkers of osteomyelitis, including IL6R, MMP8, TNFRSF11A, IL17RB, TNFSF14, and TGFBR1." (PMID 41050653, 2025).
ovarian clear cell cancer (1 paper, 2019). An invasive malignant neoplasm that arises from the ovary and is characterized by a predominance of clear and hobnail malignant epithelial cells. "siRNA mediated inhibition of IL-6R or anti-human IL-6R antibody (tocilizumab) reduced pY-STAT3 and MMP-9 expression levels suggesting that interference of STAT3 signaling in ovarian clear cell carcinoma could be an effective therapeutic strategy." (PMID 31861720, 2019).
overnutrition (1 paper, 2023). An imbalanced nutritional status resulting from excessive intake of nutrients. "Overnutrition during pregnancy and lactation in mothers did not significantly alter the levels of IL6-R in the prefrontal cortex in the offspring." (PMID 38201896, 2023). "Overnutrition during pregnancy and lactation in the mothers did not significantly alter the levels of IL6-R in the hypothalamus in the offspring." (PMID 38201896, 2023).
pituitary adenoma (1 paper, 2025). "Interestingly, IL6R signaling through the JAK2/STAT3/MMP9 axis was previously reported to promote the invasion of pituitary adenoma cells." (PMID 40002253, 2025).
pleural tumor (1 paper, 2023). "Further, addition of the IL-6Rα antagonist tocilizumab to cultures containing CFF completely abrogated tumor EMT, driving tumor cells to transition to epithelioid morphology and indicating that pleural tumor cells have the plasticity to revert from mesenchymal to epithelial states (MET)." (PMID 37063842, 2023).
polycystic kidney disease (1 paper, 2013). A usually autosomal dominant and less frequently autosomal recessive genetic disorder characterized by the presence of numerous cysts in the kidneys leading to end-stage renal failure. "The results also showed that IL6 and IL6R were up-regulated in both human polycystic kidney disease (PKD) and in a rat PKD model." (PMID 23883183, 2013).
primary immunodeficiency diseases (1 paper, 2018). "Our results further suggest, most likely for the first time, the possibility of treating primary immunodeficiency diseases and inflammatory diseases by simultaneous use of autologous Treg cells and anti-IL-6R." (PMID 29386580, 2018). "Furthermore, we demonstrate the therapeutic feasibility of combining autologous Treg cells and anti-IL-6R for the treatment of primary immunodeficiency diseases such as XLP-2." (PMID 29386580, 2018). "Therefore, a combination treatment of anti-IL-6R with autologous Treg cells should be effective in treating the inflammation and pathology of primary immunodeficiency diseases, bypassing the need to re-introduce the respective WT version of the defective gene into Treg cells." (PMID 29386580, 2018).
progeria (1 paper, 2022). "This theory is supported by the finding that, in the SAMP8 mouse strain (a progeria model), spleen weight and CRP levels were associated with a reduction in IL-6 and IL-6R expression in bone tissues as compared to a wild type control strain." (PMID 36458163, 2022).
psittacosis (1 paper, 2022). "We also noted the elevated expression level of IL6R in lymphocytes, suggesting that the IL-6/IL6R axis may be involved in psittacosis pathophysiology." (PMID 36119044, 2022).
psychomotor delay (1 paper, 2025). "Furthermore, IL6R gene polymorphism has been characterized for psychomotor delay in preterm infants." (PMID 39906903, 2025).